MIR3201 (microRNA 3201)
Synonyms: hsa-mir-3201
Gene: MicroRNA gene on chromosome 22 (48,274,364 to 48,274,415, forward strand). Ensembl gene ENSG00000266508.
Diseases named in the same sentence as MIR3201 in open-access papers:
MIR3201 is named in the same sentence as 1 disease in open-access papers, as found by Europe PMC text mining. Sharing a sentence is not in itself a finding about the gene and the disease. The quoted sentences say what the papers report.
epithelial ovarian cancer (1 paper, 2018). "Interestingly, MIR3201 was significantly downregulated in recurrent epithelial ovarian cancer (EOC), when compared to primary EOC." (PMID 29938003, 2018).